RN7SL414P (RNA, 7SL, cytoplasmic 414, pseudogene)
Gene: Miscellaneous RNA gene on chromosome 2 (45,569,199 to 45,569,492, reverse strand). Ensembl gene ENSG00000239396.
Homologues: Orthologues: macaque Metazoa_SRP (80% identical). Paralogues in human: RN7SL3 (87% identical), RN7SL1 (86% identical), RN7SL2 (85% identical), RN7SL47P (82% identical), RN7SL218P (81% identical), RN7SL566P (81% identical), RN7SL45P (81% identical), RN7SL597P (81% identical), RN7SL11P (81% identical), RN7SL230P (81% identical), RN7SL296P (81% identical), RN7SL357P (80% identical), and 706 more.